TLR4 (toll like receptor 4)
Diseases named in the same sentence as TLR4 in open-access papers (continued):
Sharing a sentence is not in itself a finding about the gene and the disease.
Sepsis (continued). "Upregulation of tubular FABP4 in septic AKI is dependent on TLR4/c-Jun signaling activation, and FABP4 mediates sepsis-induced RTEC injury, likely by forming a positive feedback loop with c-Jun to aggravate inflammation and apoptosis." (PMID 35410456, 2022). "The migration of neutrophils to the kidney during sepsis is dependent on the activation of TLR2, TLR4 and the adapter molecule-MyD88." (PMID 36010680, 2022). "In short, there was an eminent value of MAPK14 in the diagnosis of sepsis in children, while HMXO1 and TLR4 still need to be further explored in children." (PMID 35844488, 2022). "Murine studies demonstrated that endotoxin uses both TLR4 and caspase-11/gasdermin D (GsdmD) pathways to induce the release of HMGB1 from hepatocytes—the major source of circulating HMGB1 in sepsis." (PMID 35160068, 2022). "For example, it is well known that TLR4 and TLR2 play an important role in mediating the development in sepsis-induced myocardial injury." (PMID 35721566, 2022). "The AUROC for the diagnosis of sepsis for HMOX1 and TLR4 ranged from 0.77 to 0.81, while the AUROC of MAPK14 reached 0.935 and 0.941 in the training and validation sets." (PMID 35844488, 2022). "One previous study showed that simvastatin improved endothelial permeability and mitigated sepsis-induced ALI, oxidative stress, and apoptosis by inhibiting the Bax, caspase-3, and toll-like receptor 4 (TLR4)/NF-kB signaling pathway." (PMID 35269738, 2022). "Sepsis is prone to AKI, and the mechanism is related to the activation of toll-like receptor 4 (TLR4)/nuclear factor-kappaB (NF-κB) signaling pathway by bacterial products to produce a large number of inflammatory factors." (PMID 36263441, 2022). "In a classic Sprague‒Dawley rat model of sepsis peritonitis, resveratrol significantly decreases LPS-induced expression of NF-κB, TNF-α, IL6, IL-1β, and TLR4 and increases the expression of p-PI3K, p-AKT, and p-mTOR in the myocardium." (PMID 36483739, 2022). "We also observed that ISM1+ cells express TLR4, TLR5, and TLR9, and, in a mouse model of sepsis induced by P. aeruginosa, we observed that all the LSK and ISM1+LSK cells were affected." (PMID 35402623, 2022). "Several signaling pathways are involved in the pathogenesis of sepsis-induced myocardial injury, such as PI3K/AKT, MAPKs, TLR4/MyD88/NF-κB, and gp130/JAK/STAT." (PMID 35721566, 2022). "Selective TLR4 antagonists as Eritoran (E5564) and TAK-242 were first progressed to clinical trials for the treatment of sepsis and have been discontinued in different phases." (PMID 35762086, 2022). "In sepsis, platelets often show high expression of surface-inflammatory markers, including P-selectin, CD40L, and toll-like receptor 4 (TLR4), as well as aggregation of platelet-leukocytes and their subpopulations." (PMID 35464001, 2022). "Individuals with sepsis often show a high surface expression of platelet P-selectin, CD40L, and TLR4." (PMID 35464001, 2022). "Not all targets in the sepsis pathway are related to glycocalyx, and there are 6 targets (SI, ROCK1, TLR4, VEGFA, HPSE, and LGALS3) of active ingredients not only related to glycocalyx, but also involved in the sepsis pathway." (PMID 36062176, 2022). "The present study analyzed different ferroptosis-related DEGs in sepsis and healthy controls and explored the clinical value of three hub genes (HMOX1, MAPK14, TLR4) in the early diagnosis of sepsis." (PMID 35844488, 2022). "Furthermore, our findings suggested that TLR4-mediated the hyperactivation of ER stress, via activating the ATF6/CHOP pathway, might be one of the mechanisms associated with Paneth cells loss and dysfunction during intestinal barrier impairment of sepsis." (PMID 36088483, 2022). "For example, TLR2 is associated with systemic lupus erythematosus (SLE), sepsis, psoriasis; TLR3 with sepsis; TLR4 with SLE, sepsis, and psoriasis; TLR5 with psoriasis; TLR7 with SLE, stroke, and psoriasis; and TLR9 is involved in SLE, sepsis and psoriasis." (PMID 34203170, 2021).
Sepsis (continued). "They showed that SAA1 via the TLR2/TLR4/NF-κB signaling pathway mediates C2C12 myotube atrophy in vitro and sepsis-induced muscle atrophy in mice in vivo." (PMID 34572540, 2021). "Toll-like receptor 4 (TLR4), the mammalian receptor for LPS, plays a beneficial role in controlling bacterial infections but is also a main driver of sepsis." (PMID 34599159, 2021). "It is thus plausible that the TLR4/MyD88/PLD1 axis mediates increases in PA pools that serve as substrates for lipin-1 during the events of macrophage proinflamatory activation and sepsis development described in this study." (PMID 34757442, 2021). "IL-33 controls neutrophil recruitment during sepsis by preventing downregulation of CXCR2 and inhibition of chemotaxis induced by the activation of TLR4 in mouse and human neutrophils." (PMID 33673387, 2021). "In a sepsis model of renal injury, TOLLIP inhibited LPS-induced TLR4 signaling by suppressing IRAK1 activation." (PMID 33467524, 2021). "Also, due to the key role that TLR4 plays in activating the signaling pathways that lead to the secretion of proinflammatory cytokine, this gene has been suggested as a very attractive therapeutic target for inflammatory diseases, such as sepsis in human and equine." (PMID 34733317, 2021). "TLR4 signaling pathway, including TLR4/NF-κB and TLR4/IRF3 pathways, contributes to the pathogenesis of sepsis, and the signaling is activated by LPS stimulation." (PMID 33869780, 2021). "Despite these limitations, our current study compared three DBA/2 stocks in the sepsis model using LPS (which is not only a commonly used model ), but also LPS is a specific toll-like receptor (TLR) pathway such as TLR4." (PMID 33407886, 2021). "KLF4 down‐regulation resulting from promotion by TLR4 of ERK1/2 phosphorylation leads to elevated ITGA2B expression, which underpins the inflammatory response in sepsis." (PMID 33369167, 2021). "However, it is still unknown whether TLR4 inhibition decreases apoptosis in sepsis." (PMID 34733114, 2021). "In sepsis-induced AKI, elevation of renal TLR4 was reported in proximal and distal tubules and in peritubular and glomerular capillaries." (PMID 33467524, 2021). "Collectively, these results explain the down‐regulation of KLF4 in sepsis, namely via TLR4 promotion of ERK1/2 phosphorylation, and identify ITGA2B as the downstream gene of KLF4, thus highlighting the anti‐inflammatory role of KLF4 in sepsis." (PMID 33369167, 2021). "Pathogenic factors in sepsis such as LPS, after binding to TLR4, result in dysregulated inflammatory responses through complex immune activation, so targeting immune activating responses that inhibit neuroinflammation may be protective against BBB disruption by sepsis." (PMID 34804998, 2021). "E3 ligase Cblb inhibits the MyD88-dependent Toll-like receptor 4 (TLR4) signaling and attenuates acute lung inflammation induced by polymicrobial sepsis." (PMID 34712740, 2021). "The nuclear protein high mobility group box 1 protein (HMGB1) is also released during severe COVID-19, ALI/ARDS and sepsis and drives TLR2 and TLR4 activation." (PMID 33672738, 2021). "Characterising the Treml4 gene knockout mice revealed new insights into the relative roles of TLR4 and TREML4 in inducing the inflammatory cytokine storm during sepsis." (PMID 33336149, 2020). "Here we first provided the regulatory network of NEAT1/miR-17-5p/TLR4, revealing novel theoretical basis for application of NEAT1 in sepsis treatment." (PMID 32099901, 2020). "The DE miRNAs (miR-1246, miR-200, miR-223, miR-29b, and miR-145) reported earlier in sepsis patients, for example, contribute to regulation of signaling molecules (IKKα, MAL, TRAF6, MyD88) in the TLR-4 pathway during LPS exposure." (PMID 33113825, 2020). "During sepsis, SAA1 is increased in muscle and directly acts on myocytes via the TLR2/TLR4/NF‐κB p65 axis." (PMID 31441598, 2020).
Sepsis (continued). "In sepsis, TNF-α is related to organ dysfunction and increased lethality, while MIF upregulate TLR-4 and TNF-α in macrophages." (PMID 33110395, 2020). "This synthetic lipid A analogue which prevents LPS from activating TLR4, hypothetically preventing propagation of systemic inflammatory response syndrome (SIRS) characteristic of sepsis." (PMID 33679711, 2020). "QX1 formula treatment significantly inhibited the sepsis-induced activation of CaMKII, MAPK (P38, ERK1/2, and JNK), and TLR4/NF-κB pathways and promoted the activation of AKT." (PMID 32908632, 2020). "In addition, we also found that mir-146a can reverse the activation of the TLR4/NF-κB pathway caused by CRNDE, and the mir-146a inhibitor can reverse the effect of CRNDE siRNA, suggesting that CRNDE activates the TLR4/NF-κB pathway through regulating mir-146a during the sepsis-induced AKI process." (PMID 32399391, 2020). "TLR4 is one of the most studied members of the TLR family, which plays a pivotal role in the signal transduction of sepsis-induced inflammatory response." (PMID 32908632, 2020). "In conclusion, the QX1 formula improved cardiac dysfunction in sepsis mice by inhibiting calcium, MAPK, and TLR4 signaling pathways, activating PI3K/AKT pathways, and reducing the subsequent release of inflammation cytokines." (PMID 32908632, 2020). "Autophagy is initiated early after the onset of sepsis and mainly involves the AMPK and MAPK signaling pathways upon TLR4 and TLR9 activation." (PMID 33139717, 2020). "In the pathogenesis of sepsis, increased lncRNA NEAT1 binds to Let-7a competitively, and TLR4 is released from Let-7a, which is activated and stimulates downstream signals, leading to severe inflammatory responses." (PMID 31664225, 2020). "To further investigate the molecular mechanism underlying the regulatory roles of sesamin in the inflammatory effects on sepsis, we used RT-qPCR and Western blotting to evaluate the HMGB1/TLR-4/IL-33 signalling pathway." (PMID 32893702, 2020). "Platelets abundantly express surface TLR4, and platelet-TLR expression has also been shown to increase in patients with ACS, sepsis, community-acquired pneumonia and is modulated during Crohn’s disease during the acute and remission stages." (PMID 32858930, 2020). "Here, we show that TLR2, TLR4, CD36, P2RX7, VIMP, and SCARB1 are also expressed in myocytes and muscle and that muscular expression of TLR2, TLR4, CD36, and VIMP increases during sepsis." (PMID 31441598, 2020). "A small-molecule-specific inhibitor for TLR4, TAK-242 (Resatorvid), has been terminated under clinical trials in patients with sepsis-induced cardiovascular and respiratory failure due to safety and efficiency concerns (NCT00633477)." (PMID 31582899, 2019). "Moreover, our study, for the first time, reports that from binding affinity, molecular docking and SEAP assay experiments, isorhamnetin directly interacts with MD-2, implying that this compound could be a potent therapeutic candidate for the treatment of TLR4-mediated inflammation and sepsis." (PMID 31689976, 2019). "During sepsis, the increased synthesis of circulating lipopolysaccharide (LPS)-binding protein (LBP) activates LPS/TLR4 signaling in renal resident cells, leading to acute kidney injury (AKI)." (PMID 31357597, 2019). "LL-37 can sequester lipopolysaccharides (LPS) to decrease signaling by Toll-like receptor 4 (TLR4), and it has been demonstrated to prevent sepsis in animal models." (PMID 31506312, 2019). "In this study, we aimed to investigate neutrophil and monocyte CD11b/TLR4 expression and ROI production following LPS stimulation in pediatric sepsis patients ex vivo and to investigate the effect of APC treatment on these responses." (PMID 31612119, 2019). "Functional Toll-like receptor 4 (TLR4) has been characterized in human and murine platelets indicating that platelets play a role in inflammation and hemostasis during sepsis." (PMID 31307465, 2019).
Sepsis (continued). "The failures of anti-toll-like receptor 4 antibody, recombinant activated protein C, and anti-TNF-α therapies in clinical trials require a rethinking of sepsis’ pathophysiology and therapeutic strategies." (PMID 29760707, 2018). "Therapies with anti-Toll-like receptor 4, anti-TNF-α, and activated protein C failed in clinical trials, requiring a rethinking of sepsis pathophysiology." (PMID 30538802, 2018). "TAK-242 was developed as a small-molecule selective inhibitor of TLR4 signaling that suppresses the increase in serum cytokine levels TNF-a, IL-1, and IL-6 in murine and porcine models of sepsis, as well as in LPS challenged healthy volunteers." (PMID 30405628, 2018). "In the setting of polymicrobial sepsis, most studies in the past investigated the role of TLR2 and TLR4 as mediating a systemic inflammatory response." (PMID 30364002, 2018). "Evidence came from the observation that the expression of both TLR2 and TLR4 was up-regulated during their ligand stimulation in monocytes from healthy subjects, as well as in PBMC from sepsis patients." (PMID 28769820, 2017). "The results presented here provide a rationale to test the effects of TLR4 and TNF-α antagonists on LPS-induced muscle wasting in sepsis or metabolic endotoxemia patients." (PMID 28742154, 2017). "Furthermore, the identification of platelet TF and TLR4 as regulators of the effect of E. coli O111 might represent a novel therapeutic target to reduce the devastating consequences of the hemostatic disorder during sepsis." (PMID 28957360, 2017). "Induction of endoplasmic reticulum stress is also reported to be involved in sepsis/CIRP release-induced acute lung injury, which can be blocked in TLR4 KO or CIRP KO mice, suggesting that CIRP can regulate ER stress through TLR4 signaling pathway." (PMID 29134130, 2017). "Apoptosis, a major cause for DC depletion, was significantly enhanced in lethal sepsis, which was further identified as TLR2 and TLR4 dependent, since it was prevented in TLR2−/− and TLR4−/− mice." (PMID 29326712, 2017). "Moreover, it has been reported that histones and myeloperoxidase could be responsible for NET-induced endothelial dysfunction, and histones can also interact with TLR2 and TLR4 to induce cytokine production via MyD88 signaling, contributing to the systemic inflammatory response observed in sepsis." (PMID 27199981, 2016). "The expression levels of cell surface TLR2 and TLR4 on PMN is usually up-regulated upon stimulation by bacterial products, LPS or lipopeptides, as well as during sepsis." (PMID 27802348, 2016). "After confirming that TLR4 and CD14 are critical in transducing sepsis mediated ALI, we now demonstrate that intrapulmonary αvβ3 is increased by polymicrobrial sepsis in a TLR4, CD14 dependent fashion." (PMID 27349568, 2016). "Inflammation induced by CLP in a mouse model activates toll-like receptor 4 (TLR4) in the liver leading to progression of acute liver failure and worsening of sepsis." (PMID 27293313, 2016). "The etiology of sepsis-induced AKI is multifactorial, but dependent, in part, upon intrarenal TLR4 mediated cytokine induction." (PMID 26990086, 2016). "Toll like receptor 4 (TLR4), together with its co-receptor CD14, plays a central role in innate immune response after engagement with lipopolysaccharide (LPS) during sepsis by triggering a signaling cascade for inflammation." (PMID 27142532, 2016). "Whole blood from sepsis survivors and controls was either incubated with the T cell activator α-CD3/28, or the monocyte/macrophage-activators LPS (via TLR4) or zymosan (via TLR2/Dectin-1)." (PMID 27056672, 2016). "Modulation of the monocyte response during sepsis occurred despite preservation of LPS binding to monocytes and of TLR2 and TLR4 expression on the monocyte cell surface." (PMID 26879814, 2016).
Sepsis (continued). "On the other hand, studies demonstrated that TLR4−/− mice were protected from endotoxin shock induced by E. coli, thus supporting TLR4 as a possible target for therapeutic intervention in sepsis." (PMID 27293318, 2016). "IFN-β1 is produced through the TRIF-dependent pathway by TLR4 or TLR3 activation, and inhibition of IFN-β1 signaling reduces the mortality after CLP-induced sepsis." (PMID 25766838, 2015). "Whereas some consider TLR4 signaling to be prosurvival for DCs, others have reported proapoptotic roles of TLR2 and TLR4 in polymicrobial sepsis." (PMID 26440998, 2015). "When DCs were stimulated with TLR2 agonist (Pam3Cys) or TLR4 agonist (LPS) or TLR9 agonist (CpG-DNA), mRNA levels of both Il12 p40 and Il12p35 from sepsis splenic DCs were significantly lower than that from sham splenic DCs." (PMID 25821827, 2015). "The contribution of absorbed sCD14 on platelets to complement LPS/TLR4 signalling and the subsequent production of proinflammatory products increase our understanding of platelet activation by bacterial products, and may provide a new direction for treatment of patients with bacteraemia/sepsis." (PMID 25636826, 2015). "Blockade of the interaction between LPS and TLR4 signal pathway decreased TNF-α levels in LPS induced SIRS model and E. coli induced sepsis model." (PMID 26798659, 2015). "Although the antagonist to TLR4 represents an emerging promising target for the treatment of sepsis; however, the role of the PI3K pathway under TLR4-null conditions is not well understood." (PMID 24618279, 2014). "Furthermore, according to the recent evidences, TLR4-mediated elevations in the expression of these cytokines in astrocytes in the central nervous system (CNS) and glia cells can initiate and propagate several debilitating disease states such as sepsis and chronic pain." (PMID 24602493, 2014). "In the present study, we aimed to investigate the renal effects of a TLR4-inhbitor, TAK-242, in experimental sepsis." (PMID 25182709, 2014). "Based on all these findings, a potential role as adjunctive therapy in severe sepsis and septic shock has been suggested for TAK-242 and other drugs targeting the TLR-4 pathway." (PMID 24410883, 2014). "Toll-like receptors (TLR) signaling like TLR4 and TLR2 is the key pathway in sepsis pathophysiology." (PMID 25054155, 2014). "The aim of our study was to analyze the expression of TLR2, TLR4 and TLR9 in patients with symptoms of sepsis after intensive induction chemotherapy for AML." (PMID 25412934, 2014). "A statistical significance was observed between rs11536889 in TLR4 gene and rs2563298 in CD14 gene in patients with sepsis and controls." (PMID 25394369, 2014). "TLR4 and TLR2 are favorite targets for developing anti-sepsis drugs, and antagonistic compounds have shown efficient protection from septic shock in pre-clinical models." (PMID 24302927, 2013). "Mainly for historical reasons and because of their ligand specificity, TLR4 and to a lesser extent TLR2 are the favorite targets for developing anti-sepsis drugs." (PMID 24302927, 2013). "Our results show that postconditioning with sevoflurane using an experimental in vitro model of sepsis exerts protective effects on cell viability, reducing TLR2 and TLR4 expression as well as inflammatory markers in human endothelial cells." (PMID 23552565, 2013). "Results from clinical trials evaluating anti-TLR4 and anti-TLR2 approaches are presented, discussing the challenges of study design in sepsis and future exploitation of these agents in infectious diseases." (PMID 24302927, 2013). "Herein, we will review the most popular agonist (TLR3, TLR5, TLR7, TLR8, TLR9) and antagonist (TLR2, TLR3, TLR4, TLR9) agents used in pre-clinical and clinical models of acute and chronic infections, including sepsis." (PMID 24302927, 2013). "Recent studies showed that extracellular histones are major mediators of death in animal models of sepsis and that histones activate TLR-2 and TLR-4." (PMID 22889177, 2012).